CD4 (CD4 molecule)
Diseases named in the same sentence as CD4 in open-access papers (continued):
Sharing a sentence is not in itself a finding about the gene and the disease.
cancer (continued). "This aspect may be interesting in the perspective of a clinical application of TCR transfer in selected CD4+ or CD8+ T cells for adoptive immunotherapy of cancer." (PMID 20711505, 2010). "Similarly, the ratio of Foxp3+ cells to CD4+ cells was higher, 0.29, in the cancer patients than in the controls, 0.14, p < 0.001." (PMID 19604349, 2009). "CD4+CD25high regulatory T cells (Treg) are essential modulators of immune responses, including down-modulation of immune response to pathogens, allergens, cancer cells and self-antigens." (PMID 19649263, 2009). "Thus, we believe that our identified MAGE-A4-specific CD4-helper epitope peptides will become a good tool for the application to the therapy of human cancer." (PMID 19277034, 2009). "However, they raise secondary antibody responses in cancer patients and, thereby, can guide the identification of epitopes for CD4+ MHC class II-restricted helper T cells." (PMID 20020065, 2009). "In the present study, we set out to address the questions of whether including CD4 epitopes enhances CD8 T cell responses and whether CD4 T cells can be cytotoxic to cancer cells." (PMID 19707583, 2009). "The median CD4+ count at cancer diagnosis was 280 cells/mm3 (range, 106 - 572 cells/mm3)." (PMID 19719844, 2009). "Furthermore, the high prevalence of CD4+CD25+ T regs is closely associated with a poor prognosis in ovarian or pancreatic cancer." (PMID 18087278, 2008). "We describe here how this has resulted in the development of three mAbs that are now in Phase III clinical trials in various cancer indications: zano-limumab (directed against CD4), ofatumumab (directed against CD20) and zalutumumab (directed against epidermal growth factor receptor, EGFR)." (PMID 18702090, 2008). "The CD4+/CD8+ ratios were lower in the cancer groups than in the control group." (PMID 17338814, 2007). "In conclusion, we found that infiltrating CD8+ T cells and CD4+ T cells in NSCLC may cooperate to suppress cancer progression and their presence together appears to be an independent favourable prognostic factor in this disease." (PMID 16421594, 2006). "CD4+ T cells play a central role in orchestrating the immune response to cancer." (PMID 16421594, 2006). "However, the main role of CD4+ T cells in the immune response to cancer is to prime CD8+ cells and maintain their proliferation." (PMID 16421594, 2006). "Among 109 NSCLC specimens, the mean number of infiltrating CD8+ T cells in cancer stroma was 152±107 (median 148, range 6–566), that of CD8+ T cells within cancer nests was 14±25 (median 2, range 0–121) and that of CD4+ T cells in cancer stroma was 169±152 (median 134, range 0–626)." (PMID 16421594, 2006). "We found the highest number of CD4 responders in the small group of patients with cancer." (PMID 15986031, 2005). "All these indicated that CD4+CD25+ TR cells maybe an attractive target to restore or improve immune function in cancer treatment." (PMID 15679891, 2005). "Based on phenotypic characteristics, this population of lymphocytes accounts for 5–10% of all CD4+ T cells in the peripheral circulation of healthy individuals, but in patients with cancer, peripheral mononuclear cells (PBMC) may contain up to 25–30% of Treg." (PMID 15714205, 2005). "Additionally, high levels of infiltration were not identified in specimens from benign diseases, consistent with the cancer-specific activity of CD4+ and CD8+ T cells and DCs." (PMID 14583778, 2003). "CD4+ T cells were distributed mainly along the invasive margin and in the cancer stroma." (PMID 14583778, 2003). "In vitro stimulation of human T-cells from some normal individuals or cancer patients with mutant ras peptides results in the expansion of CD4+ and CD8+ precursors, which may exhibit cytotoxicity against autologous or MHC-matched, antigen-bearing target cells." (PMID 12592366, 2003). "Intratumoural CD4+ T-lymphocyte infiltrate was associated with poor cancer-specific survival, independent of grade, in this cohort." (PMID 14612901, 2003).
cancer (continued). "CD4+, CD8+ and CD4+ CD8+ (double positive) TIL clones were established from cancer patients." (PMID 8855979, 1996). "Tregs, comprising a minor subset of CD4+ T cells, play a pivotal role in sustaining self-tolerance of the immune system via modulating the proliferation and differentiation of effector cells, not only in the context of cancer, but also in inflammatory diseases." (PMID 40567611, 2025). "In support of the idea of a context-dependent role of TILs in cancer, a more sophisticated approach (called Ecotyper) for immune deconvolution and inference of tissue cellular communities (“ecotypes”) suggested a significant role of CD4+ T cells in SCC pathogenesis using the same TCGA dataset." (PMID 41007768, 2025). "Besides direct cancer cell killing, the engagement of effector lymphocytes CD8+ T, CD4+ T, and NKT cells and the presence of associated proinflammatory molecules in the TME suggests that TILT-517 efficiently triggered elements of innate and adaptive immune response." (PMID 40589567, 2025). "Similarly, the EPIC analysis revealed a negative correlation with B cells and CD4+ T cells, while showing a positive correlation with cancer-associated fibroblasts (CAFs) and macrophages." (PMID 40114922, 2025). "Compared with those in the pCR group, the numbers of CD4+ T cells (nonregulatory), CD4+ Th1 T cells and follicular helper T cells in non-pCR patients were significantly lower, whereas the numbers of cancer-associated fibroblasts and endothelial cells were significantly greater." (PMID 40691458, 2025). "Changes in immune response markers, such as reduced CD4+ T cells, impaired NK cell function, and immune checkpoint molecules like programmed cell death protein 1 (PD‐1), programmed death‐ligand 1 (PD‐L1), and lymphocyte activation gene 3 (LAG3), have been implicated in cancer progression." (PMID 40236776, 2025). "Further supportive of the notion that CD4 T cells sustain cancer cells in a senescent-like state, tumors from mice treated with the triple combination exhibited persistent SA-β-galactosidase positivity through 28 days of treatment, which was diminished upon CD4 T-cell depletion." (PMID 40299790, 2025). "However, few cancer vaccines have been designed to exclusively target CD4+ T cells so far." (PMID 40543509, 2025). "Some cancer mutations gave rise to neoantigens that were immunogenic for both CD8+ and CD4+ T cells and were recognized in the context of several different restriction elements, showing that concurrent TCR- and phenotype-diverse immune responses can be mounted against a single cancer mutation." (PMID 39762422, 2025). "However, few vaccines are specifically designed to target CD4+ T cells in human cancers." (PMID 40543509, 2025). "The introduction of ABT-containing therapy facilitated a progressive decline in HIV-1 RNA from 106 copies/mL to complete suppression by May 2024, accompanied by steady improvements in CD4 + T cell counts despite concurrent chemotherapy and targeted cancer therapy." (PMID 40251661, 2025). "The description of SFB-specific Tr1-like cells in the small intestine was surprising, as this CD4+ T cell subset, characterized by abundant IL-10 secretion in the absence ofFoxp3expression, has only been described in the context of chronic antigen stimulation, such as chronic infection or cancer." (PMID 40747421, 2025). "Therefore, the finding that the in vitro-generated CD4+ T cells are cytotoxic suggests that the vaccination-induced T cell response comprises CD4+ T cells with killing capacity towards RhoC, at least as judged by in vitro assays using class II-expressing cancer cells as targets." (PMID 40333248, 2025).
cancer (continued). "Additionally, we found a positive association between TKT and macrophages in most cancers and a negative correlation with some effector immune cells, such as resting CD4+ memory T cells and activated natural killer (NK) cells." (PMID 40230848, 2025). "Notably, the GZMA CD4 T cell subset exhibited elevated expression of genes associated with effector and cytolytic functions in CD4 T cells, including GZMA, GZMH, GZMM, and PRDM1, while also showing moderate expression of anti-cancer-related genes such as IFNG, PRF1, and TNFSF10." (PMID 40959273, 2025). "Additionally, SF3B6 was positively related to CD4+ T helper (Th) two cells and common lymphoid progenitors in most cancer types, while it demonstrated a negative association with the infiltration of other immune cell types." (PMID 40356980, 2025). "Also in TNBC, macrophages exhibited the strongest age-related changes, including more homotypic interactions and increased communication with cancer basal cells, monocytes, CD4+ T cells and CD8+ T cells in tumors from older patients, despite their lack of ARPs." (PMID 41188599, 2025). "Thus, targeting these molecules could enhance the activation and proliferation of CD4+ T cells, improving immune responses in cancer." (PMID 40282557, 2025). "Furthermore, CD4_1, CD4_4, and CD4_6 T cells were significantly increased in both epithelial/cancer areas of patients, implying that MTC may facilitate the accumulation of CD4+ T cells in the TF areas." (PMID 40360503, 2025). "Decreased CD4 T cell counts may impair immunosurveillance and cytotoxicity against cancer cells." (PMID 39975671, 2025). "IFN-γ is a key effector cytokines for anti-tumorigenic NK, CD8 and CD4 T cells affecting cancer cells and multiple immune cells and its proper induction and signaling is essential for the success of immunotherapies in many cancers and is required for suppression of BC." (PMID 40361239, 2025). "Strategies that increase the effector potential of stem-like CD4+ T cells while overcoming suppressive influences such as regulatory T (Treg) cells and immunosuppressive niches may be essential for achieving durable responses across a broad range of cancers." (PMID 40634636, 2025). "Cancer immunology and immunotherapy are driving forces of research and development in oncology, and previous studies indicated the importance of CD4+ T cells, CD4+ T cells play an essential role in the immune system by coordinating both adaptive and innate responses (Künzli and Masopust, 2023)." (PMID 39575189, 2024). "Previous investigation have revealed that CD4+ T cells not only express key molecules associated with cytolysis (such as Granzymes [GZM] and Perforin [PRF1]) but also possess direct cytotoxicity, forming the basis for their protective immunity, including in cancer." (PMID 38533503, 2024). "Notably, CD4 T cell infiltration determined using the XECLL algorithm revealed that Th1 cell infiltration was negatively correlated with SLC25A32 expression in almost all cancer types." (PMID 39624160, 2024). "Therefore, regular monitoring of CD4 cells and CD4:CD8 ratios may provide benefit if it leads to enhanced cancer screening strategies for individuals who initiate ART late and do not achieve immune restoration above 350 cells/μL and >1.0, respectively." (PMID 38092042, 2024). "Additionally, PGAM1 expression positively correlated with infiltration levels of numerous immune cells including CD4+ T cells, CD8+ T cells, regulatory T cells, macrophages, natural killer cells, myeloid dendritic cells, monocytes and cancer-associated fibroblasts in UVM." (PMID 38434965, 2024). "Moreover, through recently studied pathways, CD4+ T cells are critical for cancer immunity." (PMID 39712007, 2024). "Over-expression of RORC resulting CD4 + T cells polarizing into Th17 cells, while Th17 cells were plastic, environmental factors could determine that Th17 cells transformed intopro- or anti-cancer phenotype." (PMID 39252305, 2024).
cancer (continued). "In addition, the successful application of Adoptive cell transfer (ACT) immunotherapy with CD4+T cells in clinical research holds immense significance for the prospective treatment of cancer patients, undoubtedly paving the way for advancements in future therapies." (PMID 38327747, 2024). "This study suggests that TRMT61A-mediated tRNA-m1A58 modification could serve as a novel “translational checkpoint” for the regulation of CD4+T cell proliferation, offering a new RNA epigenetic regulatory strategy for the clinical modification of CD4+T cell functions to treat cancer." (PMID 39687616, 2024). "In both OSCC and CRC bacteria-positive microniches, the expression of T cell surface markers, such as CD3, CD8, CD4, CD27 and CD44, was also severely compromised, while the bacterial load in the OSCC TME microniches was further associated with PD-1 overexpression in cancer cells." (PMID 39120310, 2024). "Given the observed increase in Tregs with EphB4 knockdown in the cancer cell, we investigated whether CD4+ T cells within the TME differentiate into Tregs by treating CD4+ T cells with conditioned medium from MOC2 EphB4 knockdown cancer cells in vitro and conducting flow cytometry." (PMID 39091728, 2024). "However, cancer cells can have dysregulation of normal metabolic patterns and dysregulation of sex hormone receptor expression, and the impact of AR signaling on CD4+ T cell metabolism during inflammation is unknown." (PMID 39404231, 2024). "CD8+ cytotoxic T lymphocytes (CTL) and CD4+ T cells are the effector tumor infiltrating lymphocytes (TILs) observed in resected cancer tissue and are believed to participate in the host immune response against cancer which is considered a positive prognostic marker." (PMID 38384463, 2024). "Traditionally, depending on whether or not CD4/CD8 is present, it is divided into two subgroups, namely CD4+NKT and CD8+NKT, CD8+NKT cells against malignancy are associated with a Th1-biased response and homologous CD3 T cells, while CD4+NKT are mainly associated with immune regulation." (PMID 38245747, 2024). "Thus, it could remain difficult for MHC II-restricted CD8+ or CD4+ T cells to be able to directly target a majority of cancer cells." (PMID 38545119, 2024). "However, there is still a lack of definition, epidemiology, and mechanisms of CD4+ T cell senescence, and immune dysfunction associated with CD4+ T cell disease states, including cancer remain poorly understood." (PMID 38415245, 2024). "Thus, our work identifies a critical inhibitory function of a known CD4+ T cell subset that has not been generally associated with cancer immunotherapy or cancer immune escape." (PMID 39048822, 2024). "Therefore, using the TIMER database, we first found that REEP4 was negatively correlated with the purification of cancer cells and exhibited a high positive correlation with the degree of infiltration of five different immune cells (B cell, CD4+ T cell, macrophage, neutrophil, and dendritic cell)." (PMID 38552216, 2024). "Additionally, CD4+ T cells can exhibit cytotoxic functions, directly leading to cancer cell death." (PMID 39409930, 2024). "Indeed, there is an ongoing debate regarding the involvement of CD4+ TH17 cells in cancer." (PMID 38835055, 2024). "Here we assess whether CD4:CD8 ratio and CD8 cell counts may be useful biomarkers for the risk of NADM, AIDS-defining malignancies (ADM) and specific cancers, after accounting for known risk factors of cancers and sociodemographic participant characteristics." (PMID 38092042, 2024). "It is well known that CD4+ TILs could display a double immune activity in human cancers." (PMID 36833428, 2023). "Therefore, we next assessed whether methionine uptake by cancer cells is responsible for the increased levels of PD-1 on CD4 T cells by lowering the extracellular level of methionine." (PMID 37147330, 2023).
cancer (continued). "Furthermore, minimal concentrations of TH1 cytokines were detected in the culture media from CD4+ T cells expressing nfP2X7-S or nfP2X7-L in response to co-culture with cancer cells, which was also consistent with the results of the cytotoxicity assays with CD8+ CAR-T cells." (PMID 37684239, 2023). "For both cancer types, the infiltration of cluster 1 tumors was almost twice that of cluster 2 tumors, and significant differences were observed mainly in cluster of differentiation (CD) 8+, CD4+ memory activated, follicular helper, and regulatory T cells, as well as in M1 and M2 macrophages." (PMID 38049810, 2023). "In addition, the risk score was mostly negatively correlated with the steps of the cancer immunity cycle, including the recruitment process of T cell, CD4+ T cell, Th1 cell, dendritic cell, and NK cell, whereas the recruitment of neutrophil was more active in the high-risk group." (PMID 37680641, 2023). "Thus, the elevation of CD4+CD28+T cells might imply an upregulated antitumor immune response due to the influence of cancer." (PMID 37346066, 2023). "Infiltration of CD4 memory-activated T cells may be a poor prognostic factor in many cancers." (PMID 37362244, 2023). "Also, cDC1s could prime naïve CD4+ T cells by MHC-II, while activated CD4+ T cells license cDC1s to trigger cancer-specific CD8+ T cell response in turn." (PMID 38008741, 2023). "Moreover, pre-treatment with DOX in cancer patients may be an effective strategy to boost anti-cancer immune responses by increasing antigen-specific CD4+ Th1 immune responses." (PMID 36831326, 2023). "Additionally, the distribution of STAT1, STAT2, STAT3, STAT4, STAT5A, STAT5B, and STAT6 expression in CD4+ T cells in pan-cancer were also clearly illustrated, which showed that STAT1 and STAT2 expression were notably up-regulated in CD4+ Treg cell with marker OSA1 and CD4+ T cell with ISG IFIT1." (PMID 36968603, 2023). "Therefore, our findings suggest that RNF43 expression may influence the cancer patients’ prognosis through the interaction with the infiltration of T cell CD4+ and T cell CD8+ and macrophage polarization during cancer progression." (PMID 37848933, 2023). "We speculate that it may be possible that treatment with long-acting PEG-rhG-CSF can also cause CD4 + T cells and CD8 + T cells in patients with malignancies to express G-CSF receptors, which in turn can regulate T cells and elevate lymphocyte counts through these receptors." (PMID 37070077, 2023). "Thus, cytotoxic CD4 T cells in cancer have attributes of other helper T cell subsets." (PMID 37654482, 2023). "Thus, CD4-2D3 cell line should be useful not only to evaluate TCR functional avidity in HLA class II-restricted TCRs but also to screen appropriate TCRs for clinical applications such as cancer immunotherapy." (PMID 36939853, 2023). "By applying the gene signature of SC-2 CD4+ T cells to TCGA dataset, we found that the average gene signature score of cancer types was significantly associated with the objective response rate (ORR) of the corresponding cancer types (Pearson correlation = 0.66)." (PMID 36049666, 2023). "In addition, butyrate, propionate and acetate produced by the microbiota have been shown to act as such inhibitors and also increase the cytokine production of Th1 and CD4+ T cells, which could influence apoptosis and cell cycle arrest of cancer cells." (PMID 36983053, 2023). "These 21 cell clusters could be annotated to 9 cell types (B cells, cancer cells, CD4 T cells, CD8 T cells, endothelial cells, fibroblasts, mast cells, myeloid cells and other T cells) according to specific cell markers, and the marker genes for each cell type were visualized by violin plots." (PMID 36814498, 2023).